MYD88 (MYD88 innate immune signal transduction adaptor)
Diseases named in the same sentence as MYD88 in open-access papers (continued):
Sharing a sentence is not in itself a finding about the gene and the disease.
malaria (continued). "Infection with Plasmodium yoelii, a model of acute uncomplicated malaria, had either a strong phenotype with impaired survival in Tlr2−/−, and Myd88−/− mice or no observable phenotypic difference." (PMID 26738805, 2016). "Notably, in the fetuses born from MyD88-/- infected mice malaria did not impair their weight when compared to WTinf and MyD88+/-inf mice." (PMID 30761111, 2019). "Indeed, mice bearing non-functional TLR9 or MyD88, or treated with a TLR7/TLR9 antagonist display a less pronounced inflammatory response and attenuated pathology during experimental malaria." (PMID 24453977, 2014).
psoriasis (21 papers, 2017 to 2026). An autoimmune condition characterized by red, well-delineated plaques with silvery scales that are usually on the extensor surfaces and scalp. "Specifically for imiquimod-induced psoriasis, epidermal thickening via keratinocyte hyperproliferation is linked to both MyD88-dependent and MyD88-independent mechanisms and the recruitment of various myeloid populations." (PMID 32973764, 2020). "In imiquimod-induced mouse psoriasis, andrographolide inhibited the generation of proinflammatory cytokines such as IL-23 and IL-1b and induced the autophagic proteolysis of MyD88, which controlled MyD88-dependent cytokine activation and alleviated psoriasis." (PMID 36238575, 2022). "These in vivo results demonstrate that the TLR4/MyD88/NF-κB-dependent signaling pathway is aberrantly activated in keratinocytes by NETs, and that targeting of this pathway can lead to improvement in psoriasis-like inflammation." (PMID 31024570, 2019). "Our findings also complement findings from an imiquimod-induced mouse model of psoriasis which has shown to be dependent on MyD88 signalling in macrophages." (PMID 29535706, 2018). "Our present study showed that the protein expression levels of TLR7, TLR8, MyD88, and p-NF-κB in the skin of mice induced by IMQ were upregulated significantly; consequently, TLR7/8–MyD88–NF-κB signaling was considered to play a critical role in IMQ-induced psoriasis." (PMID 31181689, 2019). "Therefore, use of astilbin to control the maturation and activation of DCs by reducing MyD88 in TLR7/8 signals may be an effective strategy to treat psoriasis." (PMID 35023281, 2022). "Moreover, the inflammatory skin disorder was restored by astilbin treatment characterized by reduced accumulation of both IL‐17‐producing T cells and expression of psoriasis‐specific cytokines in skin lesions via downregulation of myeloid differentiation factor 88 (MyD88)." (PMID 35023281, 2022). "The proinflammatory activity of NETs and LCN2 induction in psoriasis was suggested to be dependent on TLR4/IL-36R crosstalk and MyD88/nuclear factor-kappa B (NF-kB) downstream signaling." (PMID 37746070, 2023). "employed CRISPR-Cas9 technique to knock out Myd88 gene in epidermal keratinocytes, and indicated that Myd88 knockout could significantly reduce the expression of its downstream IL-1β and IL-36, which are two important factors regulating the inflammatory response of psoriasis." (PMID 36618400, 2022). "For example, paeonol inhibits the maturation and activation of DCs by reducing MyD88 and TLR8 proteins in the TLR7/8 signalling pathway, and ultimately alleviates psoriasis-like skin lesions in BALB/c mice." (PMID 35095512, 2021). "Western blot results showed that IMQ promoted the expression of TLR4, MyD88, p-NF-κB p65 and p-IκBα, while PLE could reduce the protein levels of TLR4, MyD88, p-NF-κB p65 and p-IκB α in the skin of IMQ-induced psoriasis mice." (PMID 40333872, 2025). "Regarding the fundamental role of the TLR4-NF-κB pathway in the pathogenesis of psoriasis, Flii may interfere with the binding of TLR4 to myeloid differentiation primary response protein 88 (MyD88), which thereby inhibits the NF-κB pathway." (PMID 38606161, 2024). "In IMQ-induced psoriasis skin, both S1pr2-/- and S1pr2fl/fl K14-Cre mice showed higher expressions of proinflammatory cytokines such as TNF-α, IL-17A, and IL-1β together with higher expressions of MyD88/NF-κB pathway compared to the wild-type mice." (PMID 39391307, 2024). "Thus, astilbin plays an anti‐inflammatory role in psoriasis by inhibiting maturation and activation of DCs, probably through the TLR7/MyD88 signalling pathway." (PMID 35023281, 2022). "Our data showed that psoriasis-like skin diseases activated TLR receptors based on skin lesions, which increased the expression of TLR2 and TLR4, and then activated MyD88 receptors and promoted the expression of MyD88 protein." (PMID 32090080, 2020).
injury (20 papers, 2011 to 2026). Damage inflicted on the body as the direct or indirect result of an external force, with or without disruption of structural continuity. "Concurrently, the negative regulatory effect of MUC1 on the TLR4/MyD88/NF-κB pathway has been described in other diseases, such as acute lung injury and acute kidney injury." (PMID 37880668, 2023). "Hypothermia inhibits microglial cells activation by modulating autophagy/apoptosis and the MyD88-dependent TLR4 signaling pathway after traumatic brain injury." (PMID 35873794, 2022). "Our in vitro results lead us to propose PINK1-mediated mitophagy with mtDNA release as a therapeutic target via TLR9/MyD88 signaling in mechanical stretching-induced acute lung injury." (PMID 33015037, 2020). "High expression of TLR4 and down streaming molecules such as MyD88 play an essential role in progression of LPS induced acute liver injury and act as powerful mediator of inflammatory process and innate immune activation." (PMID 28241791, 2017). "In this study, LPS upregulated expression of NF-κB and its upstream proteins (TLR4 and Myd88), while indirubin markedly alleviated NF-κB activation, which might serve as the protective mechanism in LPS-induced acute lung injury." (PMID 28525368, 2017). "In D-GalN-induced acute liver injury, the TLR4/MyD88/NF-κB signaling pathway plays a pivotal role by regulating inflammatory responses and apoptosis, thereby influencing the severity of liver injury and the repair process." (PMID 41465230, 2025). "Some previous studies have found that the expression of miR-27a in LPS-induced RAW264.7 macrophages was downregulation, and overexpression of miR-27a alleviated LPS-induced acute lung injury in mice via inhibiting inflammation and apoptosis through modulating TLR4/MyD88/NF-κB pathway." (PMID 38105216, 2023). "This interaction of TLR4 and MyD88 triggers the downstream signaling cascade leading to the activation of the nuclear factor κB (NF-κB) pathway, further releasing inflammatory cytokines such as TNF-α and IL-6, which, in turn, can result in liver injury." (PMID 25328713, 2014).
ulcerative colitis (20 papers, 2015 to 2026). An inflammatory bowel disease involving the mucosal surface of the large intestine and rectum. "The rs7744 SNP, located at the untranslated region of MyD88, has been previously associated with the development of chronic inflammatory diseases, such as ulcerative colitis, Buerger disease, and coronary artery disease." (PMID 30813592, 2019). "Colon-targeted microgels alleviate ulcerative colitis by suppressing the TLR4/MyD88/NF-κB inflammatory axis and restoring gut microbiota homeostasis." (PMID 42126727, 2026). "In summary, this study demonstrated that FPH not only could inhibit ulcerative colitis via suppressing the LPS/TLR4/MyD88/NF-κB pathway and strengthen the gut barrier via enhancing the antioxidation of the colon but also could protect against secondary liver injury accompanied by ulcerative colitis." (PMID 34966476, 2021). "Our results explore the treatment effect of CPH on ulcerative colitis via dephosphorylation of NF‐κB, TLR4, and MyD88, respectively, in CPH treatment groups." (PMID 39723032, 2024). "EGCG can inhibit the intestinal inflammatory response by reducing the severity of ulcerative colitis and maintaining the Th1/Th2 balance through the TLR4/MyD88/NF-κB signaling pathway." (PMID 29404307, 2017). "It is also possible that miR-1236-3p may target other genes during Mtb infection, such as MyD88, as confirmed in Ulcerative colitis but not in TB." (PMID 40502714, 2025).
gouty arthritis (19 papers, 2015 to 2026). "More importantly, a recent study indicated that luteolin-attenuated MSU crystal induced- gouty arthritis via inhibiting the TLR/MyD88/NF-κB pathway." (PMID 34803702, 2021). "The results of cell experiments were highly consistent with the results of the animal experiments, further suggesting that the active flavonoids can attenuate gouty arthritis by regulating the TLR4/MyD88/NF-κB pathway and NLRP3 levels." (PMID 34803702, 2021). "The TLR/MyD88/NF-κB receptor signaling pathway synergizes with the NALP3 inflammasome to activate IL-1β, which plays a key role in gout inflammation caused by MSU crystals." (PMID 34721647, 2021). "The findings of the present study imply that DLE alleviates gout by promoting uric acid metabolism and inhibiting inflammation related to the TLRs/MyD88/NF-κB pathway." (PMID 33062010, 2020). "In the current study, the decrease in the incidence of gout resulting from long-term statin use might also involve the inhibition of TLR4/MyD88/NF-κB signaling." (PMID 36873987, 2023). "In conclusion, the present study demonstrated that three active flavonoids (luteolin, luteoloside, and apigenin) from Lagotis brachystachya attenuate MSU crystal-induced gouty arthritis via inhibiting TLR4/MyD88/NF-κB and NLRP3 expression in the aspect of animal experiment and cell experiment." (PMID 34803702, 2021). "Researchers found that luteolin could reduce the inflammatory response of acute gouty arthritis via down-regulating the TLR/MyD88/NF-κB pathway." (PMID 33424592, 2020). "Therefore, we speculate that the mechanism of resveratrol in anti-gouty arthritis may involve inhibiting the NLRP3-mediated TLR4/MyD88/NF-κB pathway by regulating relevant metabolic pathways, thereby inhibiting pyroptosis and slowing down the inflammatory response." (PMID 39534253, 2024). "This led to the inhibition of the TLR4/MyD88/NF-κB pathway’s activation triggered by MSU, ultimately providing relief from gout symptoms." (PMID 38094893, 2023). "For example, the expression of miR-146a was significantly increased in patients with gout and involved in both NLRP3 and MyD88/NF-κB pathways." (PMID 37426193, 2023). "In conclusion, ELB is protective in rats with chronic alcoholic liver injury and gouty arthritis, possibly mediated by the inhibition of TLR4/MyD88/NF-κB, NLRP3, and JAK2-STAT3 signaling pathways in both the hepatic and synovial tissues." (PMID 36176434, 2022). "Our present results were partly in accordance with a previous study indicating that luteolin inhibited the TLR/MyD88/NF-κB pathway, thereby attenuating MSU crystal-induced gouty arthritis." (PMID 34803702, 2021). "Simultaneously, we evaluated the effects of DLE on ankle swelling, protein expression of TLRs/MyD88/NF-κB in the ankle joint's synovium, and the downstream inflammatory factors IL-1β, IL-6, and TNF-α in the acute gouty arthritis rats." (PMID 33062010, 2020). "In conclusion, the current study indicates that ELB exhibits a protective effect in rats with chronic alcoholic liver injury and gouty arthritis, possibly mediated by inhibiting TLR4/MyD88/NF-κB, NLRP3, and JAK2-STAT3 signaling pathways in both the hepatic and synovial tissues." (PMID 36176434, 2022). "In the present study, the effects of the active flavonoids were evaluated in rats or Raw264.7 cells with gouty arthritis induced by monosodium urate (MSU) crystal, followed by the detection of TLR4, MyD88, pNF-κB, and NLR family pyrin domain-containing 3 (NLRP3) expression." (PMID 34803702, 2021).
lung carcinoma (19 papers, 2015 to 2025). "MYD88 promoter demethylation is important in glioblastoma and is associated with increased MYD88 protein expression in lung cancers." (PMID 34017329, 2021). "One important limitation of our study is that LCLs derived from patients with lung cancer were used as reference samples in order to calculate the detection limit of the next generation sequencing based assay for the MYD88 L265P mutation." (PMID 26352266, 2015). "We defined individuals as “positive” for the MYD88 L265P mutation when the proportion of the variant allele was in excess of the background error rate (0.47%), defined using 55 lung cancer samples." (PMID 26352266, 2015). "It was found that TLR2/MyD88/NF-κB signal pathway activation via the TRAF6-TAK1 signaling axis is expressed in various malignancies including lung cancer." (PMID 40022036, 2025). "Sijunzi decoction has also been found to regulate the TLR4/MyD88/NF-κB signaling pathway and reduce the expression of PD-L1 to inhibit the growth of lung cancer." (PMID 38785969, 2024). "Studies found that nickel compounds (eg. nickel chloride) significantly activated TGF-β signaling pathway by TLR4/MyD88 and NF-κB signaling pathway, and further enhance the invasive ability of lung cancer tumor cells." (PMID 30621196, 2019). "In conclusion, the current results showed that Rosa synergistically improves the chemotherapeutic potential of cisplatin in lung cancer cells by suppressing the TLR2/MyD88/ TRAF6/NF-κB signal pathway together with the PI3K/AKT/mTOR and Gal-1 which consequently, inhibits proliferation." (PMID 40022036, 2025). "In addition, we found in the literature that the expression levels of TLR4 /MyD88 /NF-κB were significantly upregulated in clinical lung cancer samples." (PMID 39735680, 2025). "Therefore, we established an orthotopic lung cancer model using MyD88 knockout mice and confirmed that the gene expression level of Inhba in AMs was significantly decreased in the knockout mice." (PMID 36650150, 2023). "Furthermore, MyD88 is essential for Taxol-induced cytotoxicity in human myelomonocytic cells, lung cancer A549 cells and human epithelial ovarian carcinoma cells." (PMID 29144391, 2017). "Depletion of SRSF1 in human A549 lung cancer cells reduces IFN-β through the expression of alternative IRF3 spliced variants, while SF3A1 silencing leads to a decreased induction of pro-inflammatory cytokines by promoting an alternative splice form of MyD88." (PMID 27454487, 2016). "Notably, 1 out of 55 individuals from the lung cancer series used as reference samples, was observed to have a MYD88 L265P allelic fraction of 2.5%." (PMID 26352266, 2015). "The combined treatment of Rosa canina extract and cisplatin significantly inhibited lung cancer cell proliferation by downregulating PARP-1 and the TLR2/MyD88/TRAF6/NF-κB signaling pathway, as well as the PI3K/Akt/mTOR pathway." (PMID 40022036, 2025). "We accomplished this using our previously established K-ras mutant lung cancer mouse model in the presence of COPD-like airway inflammation and genetic targeting of the TLR/MyD88/NF-ĸB pathway in this setting." (PMID 37283745, 2023). "Taken together, these data suggest a link between TLR-mediated inflammation in COPD and lung cancer progression, introducing TLR/MyD88/NF-kB pathway as a key player in linking COPD to lung cancer." (PMID 37283745, 2023). "Interestingly, the profound impact of rIL-33 on tumor immunity in the LLC lung cancer model was not replicated in MyD88-/- mice, underscoring the crucial role of the MyD88 pathway in mediating IL-33’s immunomodulatory effects." (PMID 38881897, 2024). "The binding of TLR2 to the adapter protein MyD88 recruits TRAF6 which consequently promotes the activation of the NF-κB Thus, the activation of this pathway may enhance carcinogenesis and development of lung cancer in addition to regulating cancer proliferation." (PMID 40022036, 2025).
metabolic syndrome (19 papers, 2010 to 2026). A cluster of metabolic risk factors for CARDIOVASCULAR DISEASES and TYPE 2 DIABETES MELLITUS. "MyD88-deficient mice are protected from metabolic syndrome including atherosclerosis and from liver injury induced by bile duct ligation or carbon tetrachloride." (PMID 21274430, 2010). "TLR4- and MyD88-deficient mice, which are resistant to metabolic syndrome, show reduced chemokine production compared with WT mice." (PMID 21274430, 2010). "Since metabolic syndrome is usually associated with increased liver fat and low-grade inflammation, investigating the exact regulation of MyD88 in the liver might lead to finding some relevant target to tackle metabolic diseases." (PMID 31039009, 2019). "Previous research in pre-clinical models showed how a deficiency in the innate adaptor molecule Myd88 leads to impaired development of T follicular helper cells and reduced IgA production in the gut, subsequently impacting the microbiota and leading to a metabolic syndrome." (PMID 39273662, 2024). "MyD88 inhibition or IL-10 elevation in adipose tissue may represent a novel strategy for metabolic syndrome." (PMID 41898743, 2026). "This study investigates whether inclisiran can mitigate the cardiotoxic effects of anthracyclines and trastuzumab through reduction of NLRP3 activation and MyD88 signaling, independently of its effects on dyslipidemia." (PMID 40724868, 2025). "MyD88 is a key molecule in the development of metabolic syndrome including NAFLD." (PMID 21274430, 2010). "Moreover, patients with metabolic syndrome (G4) also showed elevated levels of MyD88 expression." (PMID 40862415, 2025). "Strikingly, a similar decrease in Cyp7b1 mRNA expression as well as an increase in 25-OHC level have also been reported in the liver of both ob/ob and db/db mice, strengthening the fact that the dysregulation of hepatic MyD88 might be involved in metabolic syndrome." (PMID 31039009, 2019). "Thus, an MyD88-independent pathway may be involved in the regulation of inflammation-induced metabolic syndrome." (PMID 28614714, 2017). "Studies on persons with diabetes and metabolic syndrome (MetS) have reported upregulated levels of TLR2 and MyD88 genes." (PMID 31272370, 2019). "Apigenin could attenuate dyslipidemia and subsequent atherosclerotic conditions through down-regulating SREBP-1c, SREBP-2, FAS, stearyl-CoA desaturase 1, HMG-CoA reductase, TLR-4, Npc1l1, MyD88, p-IκB-α, and NF-κB p65 which are involved in inflammation and atherosclerotic plaques formation." (PMID 38629096, 2024).